BRAF (B-Raf proto-oncogene, serine/threonine kinase)
Diseases named in the same sentence as BRAF in open-access papers (continued):
Sharing a sentence is not in itself a finding about the gene and the disease.
low grade glioma (48 papers, 2015 to 2026). A grade I or grade II glioma arising from the central nervous system. "Molecular characterization of sporadic pediatric low-grade gliomas has identified frequent alterations in the mitogen-activated protein kinas pathway, most commonly fusions or mutations in the B-raf proto-oncogene (BRAF) gene." (PMID 37720347, 2023). "BRAF inhibitors, in recent years, have played a central role in the disease control of unresectable BRAF-mutated pediatric low-grade gliomas (LGGs)." (PMID 35681673, 2022). "We also identified recurrent KIAA1549/BRAF fusions in Pilomyxoid astrocytoma tumors which is an emerging diagnostic and prognostic marker in pediatric low-grade gliomas that predicts positive response to certain MEK inhibitors." (PMID 33889297, 2021). "Previous studies found that BRAF mutations as well as KIAA1549–BRAF fusions are common in intracranial low-grade gliomas (LGGs)." (PMID 33063010, 2020). "A growing body of literature suggests that BRAF V600E mutation is a potentially targetable genetic abnormality in pediatric low-grade glioma, which is found frequently in PXA and less frequently in PA." (PMID 29797290, 2018). "Pediatric low-grade gliomas (PLGGs) are frequently associated with activating BRAF gene fusions, such as KIAA1549-BRAF, that aberrantly drive the mitogen activated protein kinase (MAPK) pathway." (PMID 29156677, 2017). "On 16 March 2023, the FDA approved dabrafenib (Tafinlar, Novartis) in combination with trametinib (Mekinist, Novartis) for pediatric patients aged 1 year and older with low-grade glioma (LGG) harboring a BRAF V600E mutation and requiring systemic therapy (NCT02684058)." (PMID 37629304, 2023). "FIREFLY-1 investigated the efficacy (arm 1, n = 77), safety, and tolerability (arms 1/2) of tovorafenib (420 mg/m2 once weekly; 600 mg maximum) in patients with BRAF-altered relapsed/refractory pediatric low-grade glioma (pLGG)." (PMID 39700439, 2025). "BRAF genomic alterations are the most common oncogenic drivers in pediatric low-grade glioma (pLGG)." (PMID 37978284, 2024). "Clinical characteristics of pediatric low-grade glioma patients receiving BRAF inhibition (BRAFi) monotherapy at Children’s Healthcare of Atlanta." (PMID 39839763, 2024). "Trial design: A phase I/II study assessed trametinib alone and in combination with dabrafenib in 139 patients with BRAF V600E-mutant low-grade gliomas (LGG) from January 2015 to December 2020." (PMID 39654184, 2024). "In a phase 2 trial, the oral type II RAF inhibitor tovorafenib exhibited an overall response rate of 67% in patients with BRAF-altered relapsed/refractory pediatric low-grade glioma." (PMID 37978284, 2024). "Among 15 tested circumscribed benign gliomas, the presence of BRAF molecular alterations was recorded in 9 cases." (PMID 37936887, 2023). "Drugs targeting MEK inhibition (MEKi) have been selected for testing in NF1- and BRAF-altered paediatric low-grade gliomas (pLGG) and for PAs in particular." (PMID 37033188, 2023). "Alterations in cell growth pathways are seen in some pHGGs, including BRAF and FGFR1 mutations and gene fusions among the TRK family (NTRK1/2/3); however, BRAF/FGFR1 perturbations are far more prominent in pediatric low-grade gliomas (pLGGs)." (PMID 30340362, 2018). "Advances in surgical and radiotherapy techniques improved the outcome of children with ependymomas, and adding BRAF inhibitors (2013) improved the management of low-grade gliomas, though longer time is needed to appreciate the impact of this paradigm shift on outcome." (PMID 39752445, 2025). "Pediatric low-grade glioma (pLGG) is essentially a single pathway disease, with most tumors driven by genomic alterations affecting the mitogen-activated protein kinase/ERK (MAPK) pathway, predominantly KIAA1549::BRAF fusions and BRAF V600E mutations." (PMID 38291372, 2024).
low grade glioma (continued). "In murine models of pediatric low-grade glioma (PLGA) and in human PLGA cells, tovorafenib has been shown to potently inhibit KIAA1549:BRAF, a truncation/fusion variant of BRAF that lacks key regulatory regions in the kinase N-terminus and as a result is constitutively dimerized." (PMID 36963492, 2023). "In consideration of this, MEK inhibitors such as selumetinib and trametinib have recently been used in the treatment of progressive and recurrent low-grade gliomas in children, demonstrating a 2-year PFS of up to 69%; their efficacy is likely to be greatest in patients with BRAF V600 mutations." (PMID 37830595, 2023). "From a molecular standpoint, it was observed that tumor cells with BRAF alterations may undergo senescence after an initial period of growth, suggesting that a subgroup of pediatric low-grade gliomas may exhibit decelerating growth kinetics over time." (PMID 32375301, 2020). "In summary, our analysis indicates a clinical indication for TIM3 modulation in patients with BRAF fusion PA or, more broadly, in MAPK-activated low-grade gliomas." (PMID 39137048, 2024). "For example, several studies on pediatric patients with BRAF- or NF1-altered progressive or recurrent low-grade gliomas (LGG), including PAs, reported on promising clinical signals for targeted treatments with BRAF or MEK inhibitors when compared to control patients receiving the standard-of-care." (PMID 37656187, 2023). "BRAF is a known oncogene that activates the RAS-MAPK signaling pathways, and has been described with numerous fusion partners, including the common KIAA1549-BRAF fusion in pediatric low-grade gliomas." (PMID 34863095, 2021). "BRAF and CDKN2A mutations have been reported to characterize HGG in a subset of pediatric patients, although BRAF abnormalities are not as frequently as described in childhood low-grade glioma." (PMID 25905044, 2015).
hepatocellular carcinoma (45 papers, 2014 to 2025). A malignant tumor that arises from hepatocytes. "Increased BRAF expression was also associated with poor relapse-free survival in hepatocellular carcinoma, lung squamous cell carcinoma, and uterine corpus endometrial carcinoma." (PMID 38919805, 2024). "The iCCA is considered the second most commonly diagnosed primary hepatic malignancy after hepatocellular carcinoma (HCC), presenting several genetic alterations, such as FGFR and IDH1/2 fusion, as well as ARID1A and BRAF mutations." (PMID 37958547, 2023). "A comprehensive analysis of liver cancer (virus-associated hepatocellular carcinoma) samples has identified new and rare mutations in B-Raf proto-oncogene (BRAF) in Japanese HCC patients, as well as BRAF V600E mutations in French HCC patients." (PMID 35163468, 2022). "Further studies showed that BRAF gene silencing inhibited the proliferation, migration, and invasion of hepatoma cells." (PMID 32449085, 2020). "Mice treated with self-inactivating LV vectors encoding truncated SOS1 and BRAF, and full-length or truncated FIGN developed hepatocellular carcinoma." (PMID 27792127, 2016). "EMT in hepatoma may be promoted by NEIL3 through activation of the BRAF/MEK/ERK/TWIST signaling pathway." (PMID 40761744, 2025). "Since the BRAF pathway played a marked role in hepatocellular carcinoma, future studies may be needed to explore the relationship between the SNHG17 and BRAF pathway." (PMID 34557456, 2021). "In addition, GAL-GNR-siBRAF can target deliver siRNA to hepatocellular carcinoma cells and knockdown the expression of BRAF and inhibit the cell proliferation, invasion, and migration significantly." (PMID 32449085, 2020). "ERK-Mediated Regulation of ncRNAs: In hepatocellular carcinoma (HCC), hyperactivation of the BRAF/MEK/ERK pathway drives tumor proliferation and drug resistance by modulating lncRNAs." (PMID 40964172, 2025). "The RAF kinase inhibitors are effective in the treatment of hepatocellular carcinoma (HCC); therefore, inhibition of the BRAF/MEK/ERK pathway has become a new therapeutic strategy for novel HCC therapy." (PMID 32449085, 2020). "Biochanin A can also be used in combination with other drugs, such as ginsenoside Rh2 or BRAF inhibitor SB590885, to inhibit the proliferation of breast or hepatocellular cancers." (PMID 36512117, 2022). "Sorafenib, a multi-target kinase inhibitor for the treatment of HCC, can directly inhibit tumor growth by blocking BRAF and MAPK signal pathways, previous studies have shown that sorafenib can effectively prolong the median overall survival of patients with advanced hepatocellular carcinoma." (PMID 35155236, 2022). "Furthermore, BRAF lncRNA may be another mechanism of tumor proliferation and tyrosine kinase inhibitor (TKI) escape in hepatocellular carcinoma (HCC)." (PMID 35719323, 2022). "Hence, these results indicated that PID1 could accelerate Sorafenib-induced Raf-1 activation and facilitate the formation of Raf-1/BRAF heterodimerization, thereby blocking AKT activation via Raf-1-dependent pathway and leading to increased sensitivity of hepatoma cells to Sorafenib." (PMID 37117198, 2023).
nevus (45 papers, 2010 to 2026). Nevus (or naevus, plural nevi or naevi, from nævus, Latin for "birthmark") is the medical term for sharply circumscribed[1] and chronic lesions of the skin or mucosa. "NAMs are more frequently associated with BRAF V600E mutations, high nevus density, and lower dermal elastosis, whereas DNMs are more often linked to cumulative sun damage, older age, and heterogeneous mutation profiles." (PMID 41375060, 2025). "The most frequently observed variants were BRAF gene, found in 19 tumors, with BRAF p.V600E detected in eight primary tumors, six metastases, and one nevus." (PMID 39912776, 2025). "The high prevalence of the mutation in acquired melanocytic nevi suggests that the BRAF mutation is an initial event in melanocyte proliferation and nevus formation." (PMID 41202496, 2025). "The BRAF mutation involves one of the two alleles in every melanocytic nevus, thus suggesting that a nevus derives from the outgrowth of a single melanocyte that acquires BRAF mutations." (PMID 39727691, 2024). "This interpretation is directly supported by the immunostaining of melanocytic nevi with an antibody (VE1) specific for BRAFV600E mutation, resulting in the detection of this genetic abnormality in all melanocytes comprising a BRAF-mutated nevus." (PMID 39727691, 2024). "Despite the claimed oncogenic role of BRAF mutations, the mutant melanocytes within a benign nevus lose their proliferative activity, as the entire benign entity comprising them stops growing and temporarily stabilizes in size." (PMID 38396984, 2024). "Evidence from molecular studies to date indicates that BRAF or MAP2K mutation leads to a conventional nevus, and subsequent CTNNB1 mutation results in the phenotypic switch to DPN." (PMID 35336833, 2022). "Mutations of the β-catenin pathway have been reported to transform the phenotype of a BRAF-mutated common nevus into that of a deep penetrating nevus, including increased pigmentation, cell volume, and cyclin D1 levels in the nucleus." (PMID 36077603, 2022). "The congenital nevi case positive for BRAF V600E mutation was a 27-years old woman with a congenital nevus sized about 4 cm on the dorsal part of the hand exposed to sunlight." (PMID 33391380, 2021). "This phenomenon may be caused by the enhanced proliferative activity of nevus cells after the BRAF gene mutation." (PMID 37156689, 2023). "The CMN were divided into a mutant group and control group according to whether there was BRAF gene mutation and were strictly matched according to gender, age, nevus size, and location." (PMID 37156689, 2023). "As such, BRAF mutations probably play a major role in acquired nevus growth promotion." (PMID 21754924, 2011). "Thus, Lin and coworkers have examined BRAF mutations in sets of single cells isolated from acquired melanocytic nevi, and observed a consistent number of nevus cells that contained wild-type BRAF, mixed with nevus cells that contained BRAFV600E." (PMID 29156643, 2017). "The AUROCMLP6 of the model was 0.79 (95% CІ: 0.74–0.84), which reflects the good consistency of the BRAF mutation risk prediction model using 6 variables, such as age, primary tumor location, histological type, ulceration, LVI, and association with a nevus." (PMID 39735251, 2024). "This oncogenic change, which makes BRAF constitutively active, is thought to drive the initial melanocytic proliferation that forms the nevus." (PMID 24212610, 2010). "The BRAF V600 mutation has been linked to younger age at diagnosis, lack of chronic UV damage, a high total body nevus count, and localization of the primary tumor on the body extremities." (PMID 38396984, 2024). "Since BRAF mutations are typically fully clonal in melanocytic nevi, cases where only the nevus was mutated may suggest the absence of a direct clonal relationship between the two lesions." (PMID 41375060, 2025).
nevus (continued). "There is a 2-step pathogenesis of melanocytomas: the initiating genetic abnormality, usually BRAF/NRAS, leading to the development of a nevus, and the subset-defining genetic abnormality leading to a melanocytoma." (PMID 40123790, 2025). "Immunohistochemical studies assessing BRAF V600E can be positive, more often in DPN that is part of a combined nevus than in pure DPN." (PMID 35336833, 2022). "RhoJ deletion in BRAF mutant melanocytes modulates the expression of the pro-apoptotic protein BAD as well as genes involved in cellular metabolism, impairing nevus formation, cellular transformation, and metastasis." (PMID 28753606, 2017). "Last but not least, considering the fact that mosaic NRAS and BRAF pathogenic variants are abundant in CMN, the researchers generally agree that they initiate congenital nevus development, but they do not trigger malignancy on their own." (PMID 34643354, 2021). "Once activated, BRAF triggers the mitogen‐activated protein kinase (MAPK) signaling cascade, leading to cell cycle progression, transcriptional upregulation, and cellular differentiation that drive the initial hyperproliferation that results in the formation of the nevus." (PMID 40509563, 2025). "Nevus cells in melanocytic lesions exhibit a different differentiation stage or altered maturation compared with normal melanocytes of the skin and may harbor genetic changes that can result in altered CSPG4 expression, as observed with anti‐BRAF immunostaining." (PMID 40700516, 2025).
colorectal adenocarcinoma (44 papers, 2010 to 2026). The most common type of colorectal carcinoma. "High CA19-9 staining was associated with advanced pT-stage, pN1, L1 (p < 0.0001 each), V1 (p = 0.0239), mismatch repair protein deficiency (p = 0.0067), and BRAF V600E mutation (p = 0.0005) in colorectal adenocarcinoma." (PMID 41820800, 2026). "BRAF mutations occur in 5–10% of patients with advanced colorectal adenocarcinomas and are associated with a poor prognosis." (PMID 35267427, 2022). "LURE analysis found RNF43 truncating mutations to have similar transcriptional signatures to BRAF mutations in colorectal adenocarcinomas." (PMID 34214079, 2021). "To assess acquisition of anoikis resistance, we selected mutated KRAS (G12V) and BRAF (V600E) oncogenes owing to their clinical and biological relevance in colorectal adenocarcinoma." (PMID 31545494, 2019). "Among the remaining five mutations is BRAF p.V600E, which is significantly associated with signatures 6 and 26 in colorectal adenocarcinoma." (PMID 30412573, 2018). "Compared with colorectal adenocarcinomas, neuroendocrine carcinomas exhibited a higher frequency of BRAF (37%) mutations, but a lower frequency of KRAS (21%) and APC (16%) mutations." (PMID 29652830, 2018). "The PBF-fixed samples of the 25 colorectal adenocarcinomas collected in the study had been routinely subjected to Sequenom MassARRAY® to screen for KRAS/NRAS/BRAF/PIK3CA mutations." (PMID 28796828, 2017). "Thus, our objective was to assess the validity of KRAS and BRAF immunodetection of mutations compared with the genotyping reference method in colorectal adenocarcinoma." (PMID 25983749, 2015). "Previous findings suggested that BRAF co-purifies with both Rictor from a murine T cell line and with Raptor in MEFs and Caco2 colorectal adenocarcinoma cells." (PMID 39223665, 2024). "The pediatric patient discussed in this study presented with metastatic, MSS, BRAF-V600E colorectal adenocarcinoma." (PMID 39626159, 2024). "We collected samples of BRAF V600E-mutant CRC patients from 7825 patients diagnosed with colorectal adenocarcinoma, who underwent surgery and genetic analysis of BRAF at Zhongshan Hospital Fudan University between June 2015 and December 2018." (PMID 36130926, 2022). "In line with previous findings in colorectal adenocarcinoma, we found MSI to co-occur with BRAF mutations in colorectal NEC (4/4 MSI harboured BRAF mutation)." (PMID 34647903, 2021). "Loss of expression of SMARCB1 has been reported in colorectal adenocarcinomas and has been associated with higher histological grade, larger tumor size, poor overall survival, MSI, and the BRAF V600E mutation." (PMID 30108113, 2018). "Olevian and coworkers comparatively analyzed poorly-differentiated CNECs and poorly-differentiated conventional colorectal adenocarcinomas for mutations in KRAS and BRAF and for DMA mismatch repair protein abnormalities." (PMID 29652830, 2018). "We extended these studies by knocking down either CRAF or BRAF in HCT-116 human colorectal adenocarcinoma and PANC-1 human pancreatic adenocarcinoma cells and measured cell survival and DNA damage following irradiation." (PMID 26333361, 2015). "In one study of colorectal adenocarcinoma, the frequency of different mutations (KRAS, BRAF, NRAS, and PIK3CA) were found to vary significantly with the location of the metastasis (lung, brain, and liver)." (PMID 23119210, 2012).